CD36 (CD36 molecule (CD36 blood group))
Diseases named in the same sentence as CD36 in open-access papers (continued):
Sharing a sentence is not in itself a finding about the gene and the disease.
atherosclerosis (continued). "High expression levels of CD36 and LX-1 have been positively associated to the level of IL-1β, accelerating the progress of atherosclerosis while SR-A was negatively correlated with IL-8." (PMID 32733941, 2020). "As a clinically relevant biological marker, CD36 is associated with cardiovascular biology (e.g., atherosclerosis, angiogenesis, and ischemia-reperfusion injury), cardiac metabolism in the uptake of free fatty acids, and inflammatory related pathologies." (PMID 32717955, 2020). "Given the fact that CD36 is associated with the formation of foam cell and atherosclerosis, overexpression of CD36 and the increase of oxLDL uptake mediated by CILP2 are likely promoting atherosclerosis." (PMID 33204392, 2020). "Our results firstly revealed the acceleratory effect of SiNPs on the progression of atherosclerosis in ApoE−/− mice, which was related to lipid accumulation caused by ER stress-mediated upregulation of CD36 expression in macrophage." (PMID 33008402, 2020). "CD36 contributes to the process of atherosclerosis because CD36 deficiency prevents plaque development in apoE-/- mice." (PMID 33261070, 2020). "The scavenger receptor and foam cell marker CD36 is a coreceptor for hepatitis C virus, another viral pathogen associated with atherosclerosis." (PMID 32852032, 2020). "Similar to Msr1, the expression of CD36 on macrophages has been linked to increased uptake of lipoproteins in atherosclerosis." (PMID 31429730, 2019). "Increased levels of soluble CD36 (sCD36) in plasma has been strongly associated with insulin resistance, T2D, dyslipidemia, and atherosclerosis in humans." (PMID 31748580, 2019). "CD36 also plays a role in atherosclerosis since CD36 is a class B scavenger protein and associated with macrophage infiltration." (PMID 31137794, 2019). "Our results conclude that IL-34 facilitates foam cell formation by increasing CD36-mediated lipid uptake and suggest a potential new risk biomarker for atherosclerosis." (PMID 30478377, 2018). "Further, it has been suggested that polarization of pro-inflammatory macrophages underlying the low-grade inflammatory state in atherosclerosis is driven by CD36 exposure to oxLDL." (PMID 30425991, 2018). "The association between monocyte/macrophage CD36 and atherosclerosis has been found in the previous studies." (PMID 27461004, 2016). "CD36 encodes a platelet receptor glycoprotein involved in different biological processes such as inflammation, atherosclerosis, and platelet activation." (PMID 27461004, 2016). "It is possible that CD36 is critical for the development of arthritis in our model similar to its role in atherosclerosis where loss of CD36 improves atherosclerosis in ApoE−/− mice by over 60 %." (PMID 27287704, 2016). "Since our main objective was to associate the membrane expression of CD36 with subclinical atherosclerosis, other molecules related with cardiovascular risk such as ox-LDL, IL-6, and TNFα were tested.Results." (PMID 25006585, 2014). "CD36 has been implicated in the pathogenesis of several diseases, including AD, atherosclerosis, and malaria, and has been identified as an endogenous negative regulator for angiogenesis." (PMID 24625061, 2014). "Studies have demonstrated that CD36-deficiency dramatically inhibits lesion development in ApoE-/- mice, and can also have a protective effect in late stages of atherosclerosis." (PMID 24324556, 2013). "The scavenger receptor CD36 has been shown to be central in facilitating monocyte/macrophage uptake of oxLDL, and appears to be linked to atherosclerosis." (PMID 24349333, 2013).
atherosclerosis (continued). "Several studies report that the expression of this 88 kDa transmembrane glycoprotein CD36 is strongly associated with atherosclerosis, angiogenesis, inflammation, lipid metabolism, platelet activation, hyperglycemia, and insulin resistance." (PMID 24282409, 2013). "ApoE knockout mice deficient in SR-A or CD36 have been reported to have similar levels of atherosclerosis to wild-type apoE knockout mice, whereas other studies have demonstrated that deletion of these receptors decreases atherosclerosis." (PMID 21904540, 2011). "In humans, subjects naturally deficient in CD36 show greater atherosclerosis, which suggests CD36 has an anti-atherogenic role." (PMID 17335569, 2007). "In murine models of atherosclerosis, ApoE-/- mice, the consequences of inactivating the gene encoding CD36 remain contradictory: a decrease in the formation of atheroma plaques in one case, and an increase in the size of atheroma plaques in another." (PMID 17335569, 2007). "Deficiency of CD36 could impair the clearance of lipoprotein lipase-mediated triglyceride 68, chylomicrons 21 and oxidized LDL 69, indicating the importance of CD36 in controlling the clearance of dietary lipid intake and reducing the risk of atherosclerosis." (PMID 40365299, 2025). "These individuals were found to have a significantly higher incidence of coronary heart disease than the general population, suggesting that CD36 deficiency may promote atherosclerosis." (PMID 40565598, 2025). "In this study, we aimed to develop a novel imaging platform for atherosclerotic plaque by constructing a molecular imaging probe that targets the lipid necrotic core using fluorescent molecules to identify high-risk plaque, based on the CD36 distribution in atherosclerosis." (PMID 40284439, 2025). "These receptors have also been reported to reduce the rate of atherosclerosis progression via NF-κB suppression that causes attenuation of pro-inflammatory cytokines production and inhibits cluster of differentiation (CD36) expression, thus reducing LDL absorption." (PMID 40944193, 2025). "For these reasons, it may be posited that CD36 deficiency may prove an effective means of ameliorating diabetic cardiomyopathy and atherosclerosis, whereas CD36 overexpression may serve to reverse ischemia-reperfusion injury." (PMID 39595068, 2024). "Moreover, previous studies have confirmed that macrophage CD36 promotes atherosclerosis, and that CD36 deficiency reduces atherosclerotic lesion formation in ECs." (PMID 38218337, 2024). "Specifically, mice deficient in CD36 are resistant to diet-induced atherosclerosis." (PMID 39156133, 2024). "The rs5956 in the CD36 gene has been associated with lower density and thickness of the atheromatous plaque, which suggests its protective effects against the development of atherosclerosis; however, it also implies a risk of plaque instability." (PMID 37239003, 2023). "Therefore, CD36 is suggested to be an essential risk factor for cardiovascular disease and a potential maker of atherosclerosis." (PMID 37760913, 2023). "The therapeutic potential for improving the lesion stability by targeting CD36 with the cyclic azapeptide MPE-298 has now been investigated in a preclinical mouse model of atherosclerosis featuring apolipoprotein E-deficient (apoE−/−) mice fed a high-fat high-cholesterol (HFHC) diet." (PMID 37332345, 2023). "The effect of Card9 deficiency on the upregulation of CD36 expression and lipid uptake might account for the accelerated atherosclerosis in Card9-deficient mice." (PMID 37528097, 2023). "Therefore, FSTL3 is linked to atherosclerosis by its role in upregulating CD36 and promoting lipid accumulation in macrophages." (PMID 36325361, 2022). "CD36 is a scavenger receptor and has been linked to the pathogenesis of atherosclerosis and Alzheimer’s disease through its recognition of modified endogenous ligands, including oxidized low-density lipoprotein (oxLDL), fibrillar amyloid-β, and soluble amyloid-β." (PMID 35526067, 2022).
atherosclerosis (continued). "However, global deletion of CD36 results in dyslipidemia, subclinical inflammation, and an increased risk of atherosclerosis." (PMID 35991116, 2022). "Moreover, circulating monocytes express increased CD36 levels in individuals with high risk to develop atherosclerosis." (PMID 35958411, 2022). "Since CD36 is a key player in metabolic diseases, like NASH, atherosclerosis 65, diabetes 66, and it can be influenced by both lipid levels and palmitoylation, CD36 palmitoylation is likely to be a crucial mechanism underlying lipid-induced metabolic disorders." (PMID 34803494, 2021). "Both global and macrophage deficiency of CD36 were found to be protective against atherosclerosis." (PMID 34888367, 2021). "Additionally, CD36 also plays a role in atherosclerosis progression, and it is associated with traditional CV risk factors." (PMID 34629330, 2021). "Changes in CD36 expression have been associated with various cardiovascular diseases, decreasing in pathological cardiac hypertrophy caused by ischaemia–reperfusion and pressure overload, and increasing in diabetic cardiomyopathy and atherosclerosis." (PMID 35050131, 2021). "CD36 deficiency in ApoE−/− mice can inhibit neointimal hyperplasia and vascular smooth muscle cells (VSMCs) proliferation, which may prevent atherosclerosis and restenosis." (PMID 33371312, 2020). "The present study provides the first evidence that β-endorphin stimulates atherosclerosis by increasing the inflammation in ECs and macrophages, mediating oxLDL-induced foam cell formation in association with CD36 and ACAT-1 upregulation, and inducing migration and apoptosis in VSMCs." (PMID 32308678, 2020). "CD36 is associated with regulation of lipid metabolism, atherosclerosis, and blood pressure." (PMID 31185924, 2019). "Interestingly, an inverse association between specific type of carcinoma and atherosclerosis has been reported 32, which made a plausible explanation from another perspective to clarify the relationship of CD36 and carcinogenesis." (PMID 31528216, 2019). "A potential mechanism might involve macrophages: two scavenger receptors implicated in atherosclerosis—CD36 and SR-A1—were upregulated in macrophages from mice fed with diets supplemented with either choline or TMAO." (PMID 31892152, 2019). "Moreover, circulating CD36 shows a general association with several cardio-metabolic conditions including atherosclerosis." (PMID 30425991, 2018). "Evidences suggest that the pathogenic role of oxLDL in atherosclerosis largely depends on CD36." (PMID 29113088, 2017). "In addition, many studies have demonstrated that the polymorphism of CD36 influences the serum lipid levels in the patients of atherosclerosis, coronary heart disease, and metabolic syndrome." (PMID 28804718, 2017). "With fatty acid uptake and oxidized LDL binding linked to fatty acid metabolism and atherosclerosis, it will be interesting to see whether CIDRα2-6 domains can prevent fatty acid uptake as a proof of principle of targeting this region of CD36." (PMID 27667267, 2016). "Given the overlap in interactions amongst CD36/SR-B2, TLRs and Pg, we hypothesized that there may be a CD36/SR-B2-dependent aspect to the mechanism of PD associated atherosclerosis." (PMID 25938460, 2015). "In addition, protease inhibitors such as ritonavir, indinavir, and amprenavir upregulate CD36, a scavenger receptor that mediates cholesterol uptake in macrophages causing aggressive atherosclerosis and in-stent restenosis." (PMID 25685591, 2015). "Previous observations have suggested that CD36 deficiency may provide a more atherogenic environment to accelerate the development of atherosclerosis, causing a significant increase in fasting levels of FFA." (PMID 21486455, 2011).
atherosclerosis (continued). "A deficiency in TGF-β, which also results in deficiency of p21 5 could result in increased expression of CD36 leading to severe atherosclerosis." (PMID 19604372, 2009). "Interestingly, the impacts of CD36 deficiency on atherosclerosis in mice were sex-specific, for example, knockout of CD36 in male mice increased carbohydrate utilization and decreased energy expenditure, while knockout of CD36 in female mice reduced atherosclerosis." (PMID 40040886, 2025). "Thus, CD36 in macrophages may be a pivotal molecule associated with foam cell formation and the development of chronic sterile inflammation in atherosclerosis." (PMID 38839811, 2024). "However, whether these CD36-independent pathways are responsible for the reduction of atherosclerosis in CD146 deficiency or anti-CD146 treatment would require further research." (PMID 28084332, 2017). "However, patients deficient in CD36, had advanced atherosclerosis." (PMID 26493158, 2016). "Moreover, the pathogenic role of oxLDL in atherosclerosis largely depends on CD36." (PMID 24766787, 2014). "In addition to CRP, CD36 is one of the key genes enriched in the cell surface binding pathway, and has been reported to be associated with inflammation-mediated diseases such as atherosclerosis." (PMID 24763700, 2014). "Furthermore, it is believed that decreased expression of CD36 in macrophages, induced by various cytokines, is linked to the development of atherosclerosis, possibly due to Toll-like receptor (TLR) pathway activation arising from the increase in cytokines, such as TNF-α." (PMID 24349333, 2013). "In summary, ADAMTS7 promotes atherosclerosis by driving SMC foam cell formation through an AP-1/PU.1/CD36 regulatory axis." (PMID 41609669, 2026). "Collectively, these findings demonstrate that EP4 regulates macrophage polarization and foam cell formation through CD36 regulation, thereby contributing to the progression of atherosclerosis." (PMID 40643540, 2025). "FABP4 and CD36 interacted closely, further confirming that FABP4 and CD36 were important mediating targets of atherosclerosis." (PMID 40824771, 2025). "Previous studies have highlighted the potential of using CD36-targeting antibodies as probes in photoacoustic imaging of atherosclerosis." (PMID 40284439, 2025). "In a diet-induced atherosclerosis model (Apoe-null mice), we observed persistently elevated mtROS levels in circulating monocytes in a CD36-dependent manner during the early stages of atherogenesis." (PMID 40250804, 2025). "In summary, our study demonstrates that EP4 attenuates the development of atherosclerosis by regulating CD36 expression, thereby suppressing foam cell formation and M1 macrophage polarization." (PMID 40643540, 2025). "In atherosclerosis research, CD36 signaling has been increasingly recognized for its key role in promoting plaque inflammation." (PMID 40284439, 2025). "As such, CD36 has been shown to contribute to a number of chronic inflammatory conditions, such as atherosclerosis, Alzheimer’s disease, and type 2 diabetes." (PMID 40512027, 2025). "Treatment with statins has been shown to decrease the CD36 expression on platelet surfaces, thus inhibiting the progression of atherosclerosis." (PMID 40002707, 2025). "This process is critically mediated by lipoprotein lipase (LPL) and the fatty acid translocase CD36, ultimately leading to reduced plasma lipid levels and conferring protection against atherosclerosis in hyperlipidaemic models." (PMID 41009610, 2025). "CD36 modulation of the intracellular lipid content in macrophages directly influences the pathogenesis of atherosclerosis and obesity 18,43,44." (PMID 40502773, 2025). "Ezetimbe, a clinically approved inhibitor of intestinal cholesterol uptake, down-regulates CD36 expression and foam cell formation, suppressing atherosclerosis development and progression." (PMID 40563926, 2025).
atherosclerosis (continued). "A previous report has revealed that nobiletin attenuated lipid accumulation and the extent of atherosclerotic lesions and further alleviated atherosclerosis by inhibiting lipid uptake via the PPARγ/CD36 pathway." (PMID 40832599, 2025). "It had been shown that in most cases, the uptake of Ox‐LDL by macrophages was mediated by CD36, which was an important mechanism of atherosclerosis." (PMID 40824771, 2025). "These oxidized particles, including MDA-LDL and oxLDL, are taken up by macrophages via CD36, promoting foam cell formation and accelerating atherosclerosis." (PMID 40867895, 2025). "Developing a genetically targeted CD36 null mouse line has played a critical role in demonstrating in vivo relevance to atherosclerosis disorder." (PMID 40040886, 2025). "Previous studies have established that CD36 influences PPARγ activity, which in turn affects various physiological processes, including atherosclerosis, liver cholesterol biosynthesis, and adipose mitochondrial biogenesis." (PMID 41267927, 2025). "In summary, deficiency of EP4 receptor in macrophages enhance foam cell formation and M1 polarization by upregulating CD36 expression, thereby accelerating the progression of atherosclerosis." (PMID 40643540, 2025). "In contrast, the surface expression of CD36 was downregulated in peripheral blood mononuclear cells in RA patients with subclinical atherosclerosis compared with RA patients with normal cIMT." (PMID 40943434, 2025). "CD36 modulation of the intracellular lipid content in macrophages directly influences the pathogenesis of atherosclerosis and obesity." (PMID 40717126, 2025). "Our results show that the abnormal expression of genes such as CD36 and ALDH2 is closely associated with the development of atherosclerosis." (PMID 41287052, 2025). "In the present study, we demonstrate that EP4 deficiency enhances macrophage foam cell formation and M1 polarization at least in part by upregulating CD36 expression, thereby exacerbating the progression of atherosclerosis." (PMID 40643540, 2025). "During atherosclerosis, activated eosinophils can regulate macrophage switching from M2 to M1, which is partly mediated by the CD36 signaling pathway." (PMID 40643540, 2025). "CD36 overexpression favors progression of different pathologies, such as atherosclerosis and cancer." (PMID 39967671, 2025). "Previous studies have demonstrated that SalB effectively inhibits the binding of CD36 to its ligand, thereby mitigating its detrimental effects in atherosclerosis and inflammation." (PMID 41357244, 2025). "Upregulation of CD36 in the Lipid and Atherosclerosis pathway suggests enhanced fatty acid transport and lipid synthesis." (PMID 40565658, 2025). "These substances interact with vascular endothelial cells and then absorb and phagocytose oxidized low-density lipoprotein and other lipids through scavenger receptor A and CD-36 to form foam cells, promote inflammation, and accelerate atherosclerosis." (PMID 41048970, 2025). "In atherosclerosis, CD36 promotes the entry of long-chain fatty acids into the mitochondria of macrophages, impairing the function of Complex V (ATP synthase) in the mitochondrial electron transport chain." (PMID 40331957, 2025). "CD36 plays a key role in regulating vascular and cardiovascular health and in the pathogenesis of atherosclerosis." (PMID 40565598, 2025). "Given the importance of CD36 in pathogenesis, it has been proposed as a therapeutic target in multiple diseases including atherosclerosis and cancer." (PMID 39967671, 2025). "Similar trends were observed for LOX-1 and CD36, where the P3 treatment led to a marked reduction in expression compared with the atherosclerosis control group (K+) and the other groups, indicating an inhibition of oxidized LDL uptake and foam cell formation." (PMID 40699832, 2025).